LINC01989 (long independently transcribed non-coding RNA 1989)
Gene: Long non-coding RNA gene on chromosome 17 (34,169,372 to 34,196,211, reverse strand). Ensembl gene ENSG00000261156.
Diseases named in the same sentence as LINC01989 in open-access papers:
LINC01989 is named in the same sentence as 1 disease in open-access papers, as found by Europe PMC text mining. Sharing a sentence is not in itself a finding about the gene and the disease.
LINC01989 shares sentences with these, for which no sentence is quoted: fibrosis (1 paper).